ANXA2 (annexin A2)
Diseases named in the same sentence as ANXA2 in open-access papers (continued):
Sharing a sentence is not in itself a finding about the gene and the disease.
liver disease (2 papers, 2024). "Continued investigation into the molecular mechanisms of ANXA2 will enhance our understanding of its roles in liver disease and support the development of targeted therapeutic strategies." (PMID 39697329, 2024). "Recent studies highlight the critical role of ANXA2 as a pivotal regulator in the pathogenesis and progression of various liver diseases, including NAFLD and HCC." (PMID 39697329, 2024). "Given its central role in pathways crucial to liver health, targeting ANXA2 represents a novel approach to treat liver diseases." (PMID 39697329, 2024). "Moreover, recent data suggest that both KRT17 and ANXA2 could be potential biomarkers for the diagnosis of liver diseases." (PMID 39273539, 2024). "ANXA2 overexpression and KRT17 nuclear translocation were also observed, supporting the role of both molecules in the progression of liver disease." (PMID 39273539, 2024).
liver steatosis (2 papers, 2021 to 2024). "Studies have found that the upregulation of ANXA2 is associated with liver steatosis, inflammation, and fibrosis; thus, hepatocytes, under the stimulation of excessive lipid accumulation and FFA, accelerate the transition to inflammation and fibrosis through ANXA2." (PMID 39683601, 2024).
low grade glioma (2 papers, 2017 to 2021). A grade I or grade II glioma arising from the central nervous system. "To avoid differences resulting from tumor heterogeneity, we also analysed the prognostic value of ANXA2 expression in low-grade glioma (LGG) and HGG among patients in the two datasets, and the conclusions were similar." (PMID 34675316, 2021).
Lyme disease (2 papers, 2020 to 2021). Lyme disease (named after the towns in the USA where the disease was first identified) is a bacterial infection caused by Borrelia burgdorferi. "Previous studies identified peptides from annexin A2, apolipoprotein B-100, thymidine phosphorylase (endothelial cell growth factor), and stromelysin-2 (matrix metalloproteinase 10) as targets of autoreactive T cells in a subset of human Lyme disease patients." (PMID 33043033, 2020).
mucinous cystadenocarcinoma (2 papers, 2014 to 2019). An invasive adenocarcinoma characterized by cystic changes and the presence of malignant glandular cells which contain intracytoplasmic mucin. "The positive expression rates of ANXA2 in ovarian serous and mucinous cystadenocarcinomas were 66.67% and 90%, respectively." (PMID 25362534, 2014).
mycoplasma infection (2 papers, 2017 to 2023). "It is speculated that Annexin A2 may work in combination with S100A10 to mediate mycoplasma infection." (PMID 37482693, 2023). "In conclusion, we found that mycoplasma infection gives rise to a MDR of human hepatocarcinoma cells and proved that this influence depends on the interaction between P37 of mycoplasma and Annexin A2 of host cells." (PMID 28976984, 2017). "However, the presence of Annexin A2 on the cell surface alone does not appear to be sufficient to mediate mycoplasma infection, as anti-Annexin A2 antibodies do not effectively block mycoplasma infection." (PMID 37482693, 2023).
nephrotic syndrome (2 papers, 2022 to 2024). A collection of symptoms that include severe edema, proteinuria, and hypoalbuminemia; it is indicative of renal dysfunction. "With regard to MCD, a recent study found IgG4 antibodies against ANXA2 in 17% of children with non-genetic steroid-resistant nephrotic syndrome in a large multicenter study in China." (PMID 38891801, 2024).
osteonecrosis (2 papers, 2018 to 2022). A none disease characterized by death of bone tissue due to a lack of blood supply. "A recent study linked a single nucleotide polymorphism (SNP) in the AnxA2 gene (rs7170178) to osteonecrosis in sickle cell patients." (PMID 29914106, 2018). "The SNP frequency of the AnxA2 gene polymorphism was higher in sickle cell osteonecrosis patients than those without osteonecrosis." (PMID 29914106, 2018).
ovarian tumor (2 papers, 2020 to 2025). "CAR(2448) induces cytotoxicity and cytokine release upon recognition of target ovarian tumour cells expressing annexin A2 in vitro, and mediates tumour clearance in a xenograft murine model." (PMID 31936170, 2020). "Consistently, 2448-28z CAR-T cells killed annexin A2-expressing SKOV3 ovarian tumor cells to greater extent than non-CAR counterparts." (PMID 40248694, 2025).
papillary carcinoma (2 papers, 2022 to 2025). A malignant epithelial neoplasm characterized by a papillary growth pattern. "Furthermore, the high expression of AnxA2 was significantly observed in non-papillary carcinoma, which is usually high-grade and invasive, compared to papillary carcinoma, which is usually low-grade and non-invasive." (PMID 36428758, 2022).
parathyroid adenomas (2 papers, 2023 to 2024). "The total percentage of immunohistochemically positive cells with ANXA2 antibody in parathyroid adenoma is 60.8%, which makes ANXA2 positive staining in sporadic parathyroid adenoma." (PMID 39064529, 2024). "Materials and Methods: Fifty-one parathyroid adenomas were analyzed for ANXA2, MED12, MAPK1 and VDR expressions." (PMID 39064529, 2024). "VDAC1, ANXA5, ANXA2, and S100-A11 proteins are increased in parathyroid adenomas." (PMID 37223014, 2023). "The aim of our study is to evaluate the quantitative expression of four gene proteins (ANXA2, MED12, MAPK1 and VDR) by immunohistochemical analysis in tissue samples of parathyroid adenoma, as well as their qualitative characteristics." (PMID 39064529, 2024). "Immunohistochemical analysis of ANXA2, MED12, MAPK1 and VDR proteins in sporadic parathyroid adenoma confirmed their expression in parathyroid cells." (PMID 39064529, 2024). "The aim of this study is to evaluate the immunohistochemical staining of ANXA2, MED12, MAPK1 and VDR in parathyroid adenoma tissue." (PMID 39064529, 2024). "ANXA2, MED12, MAPK1 and VDR proved to have a positive staining in the immunohistochemical study of sporadic parathyroid adenomas in varying intensity and allocation percentages." (PMID 39064529, 2024). "ANXA-2, ATP5H, and LMNA are examples of proteins detected in parathyroid adenomas, fact that has been verified by three different studies." (PMID 37223014, 2023).
Parkinson disease (2 papers, 2020 to 2025). A progressive degenerative disorder of the central nervous system characterized by loss of dopamine producing neurons in the substantia nigra and the presence of Lewy bodies in the substantia nigra and locus coeruleus. "The evidence suggests a potential contribution of ANXA2 to the pathogenesis of primary and secondary tauopathies, as well as Parkinson’s disease." (PMID 40141747, 2025).
prostate adenocarcinoma (2 papers, 2020 to 2023). "We found significantly lower levels of ANXA2 expression in prostate adenocarcinoma compared with normal prostate gland (Median Rank: 153; p = 7.9× 10−6." (PMID 32197509, 2020). "In the case of prostate adenocarcinoma there was 53% of samples HO-1(-)/ANXA2(+), 18.7% HO-1(+)/ANXA2(+), 9.6% HO-1(+)/ANXA2(-), and 18.7% HO-1(-)/ANXA2(-)." (PMID 32197509, 2020). "The meta-analysis combining data from the independent data sets assessed, showed that ANXA2 lies within the 1%–16% of the most consistently underexpressed genes for prostate adenocarcinoma versus normal prostate gland." (PMID 32197509, 2020).
psoriasis (2 papers, 2011 to 2024). An autoimmune condition characterized by red, well-delineated plaques with silvery scales that are usually on the extensor surfaces and scalp. "Trim33 promoted ANXA2’s interaction with p50/p65 subunits of NF-κB by catalyzing lysine 63 (K63)-linked ubiquitination of Annexin A2 (Anxa2) to stir inflammation response in psoriasis." (PMID 38688909, 2024).
scoliosis (2 papers, 2019 to 2024). A congenital or acquired spinal deformity characterized by lateral curvature of the spine. "Interestingly, two proteins previously associated with scoliosis, Annexin A2 and Calmodulin were found to interact with wtPOC5 were previously associated with scoliosis." (PMID 30845169, 2019). "Anxa2 and GFAP upregulation and increased number of LCP1-positive cells around CNS ventricles of rpgrip1l-/- juvenile fish at scoliosis onset." (PMID 39388365, 2024).
Tauopathies (2 papers, 2023 to 2025). "Annexin A2 was reported to be involved in the axonal localization of Tau and to participate in its redistribution to the SD compartment in Tauopathies." (PMID 36399251, 2023). "Published data suggest that ANXA2 may be involved in the development of tauopathy through multiple pathways." (PMID 40141747, 2025). "It is also known that FLNA and ANXA2 are involved in altering the structure of F-actin, which may also be important for the pathogenesis of tauopathies in general." (PMID 40141747, 2025). "Furthermore, there are several studies describing the participation of ANXA2 in the pathogenesis of NDs such as primary and secondary tauopathies and Parkinson’s disease (PD)." (PMID 40141747, 2025). "Collectively, our data indicated that in Tauopathies, FLNA could contribute to Tau pathology by acting on Tau and annexin A2." (PMID 36399251, 2023).
upper tract urothelial carcinoma (2 papers, 2014 to 2023). "Anxa2 was significantly increased in the urine of patients with upper tract urothelial carcinoma (UTUC) compared with healthy individuals." (PMID 37955107, 2023).
urothelial carcinoma (2 papers, 2021 to 2022). A malignant neoplasm derived from the transitional epithelium of the urinary tract (urinary bladder, ureter, urethra, or renal pelvis). "In addition, ANXA2 is also a protein that has been studied extensively, and studies have shown that ANXA2 is highly expressed in urothelial carcinoma and is associated with prognosis." (PMID 34484309, 2021).
acute liver failure (1 paper, 2024). Rapid deterioration of liver function causing encephalopathy and coagulopathy. "The data revealed that the clustering of the ANXA2+ subpopulation and cycling hepatocyte subpopulation was presented in patients with APAP‐induced acute liver failure compared to healthy controls." (PMID 39440550, 2024).
Adamantinomatous Craniopharyngioma (1 paper, 2017). A craniopharyngioma consisting of broad strands, cords and bridges of a multistratified squamous epithelium with peripheral palisading of nuclei. "The expression of ANXA2 was extremely higher in recurrent Adamantinomatous Craniopharyngioma (AdaCPs) and ANXA2+ AdaCP cells were more sensitive to tyrosine kinase inhibitor gefitinib." (PMID 29291003, 2017).
age-related macular degeneration (1 paper, 2025). Age-related loss of vision in the central portion of the retina (macula), secondary to retinal degeneration. "It is also notable that AnxA2 has been detected in glomeruli isolated from patients with C3G and in macular drusen of patients with age-related macular degeneration, disease lesions that are associated with activation of the alternative pathway." (PMID 40889685, 2025).
alcoholic liver cirrhosis (1 paper, 2012). A disorder of the liver characterized by the presence of fibrotic scar tissue instead of healthy liver tissue. "ANXA2 is involved in the plasminogen/plasmin system with fibrinolytic effects promoting clot dissolution in alcoholic liver cirrhosis." (PMID 23270325, 2012).
anaplastic thyroid carcinoma (1 paper, 2022). "Keratins 8 (KRT8) protein was reported to bind to annexin A2, a protein known to mediate apoptosis as well as the redox pathway in anaplastic thyroid carcinoma (ATC)." (PMID 36672532, 2022).
ankylosing spondylitis (1 paper, 2023). An autoimmune chronic inflammatory disorder characterized by inflammation in the vertebral joints of the spine and sacroiliac joints. "Prior studies have demonstrated that ANXA2 upregulates the expression of IL-6, which subsequently activates the ERK pathway and promotes the development of ankylosing spondylitis (AS)." (PMID 37828081, 2023).
aortic stenosis (1 paper, 2022). Aortic valve stenosis is a aortic valve disease caused by the incomplete opening of the aortic valve. "The analysis of the pericardial fluid proteome through a state-of-the-art MS instrument identified annexin A1, annexin A2, and vimentin as potential biomarkers of AF in severe aortic stenosis." (PMID 35207752, 2022).
aortic valve stenosis (1 paper, 2019). Aortic valve stenosis (AVS) is a condition characterized by narrowing of the heart's aortic valve opening. "We detected an upregulation of complement 9 (C9), serum amyloid P-component (APCS) and transgelin as well as downregulation of heat shock protein (HSP90), protein disulfide isomerase A3 (PDIA3), annexin A2 (ANXA2) and galectin-1 in patients with aortic valve stenosis." (PMID 31856737, 2019).
artery thrombosis (1 paper, 2021). "AnxA2-deficient mice provided the first in vivo evidence that AnxA2 mediates fibrin clearance, as the AnxA2−/− mice showed substantial deposition of fibrin and after induction of acute carotic artery thrombosis, displayed increased thrombosis." (PMID 33810523, 2021).
Ascites (1 paper, 2021). Accumulation of fluid in the peritoneal cavity (between the layers of the peritoneum that lines the abdomen). "For OS, age > 65 years, Child–Pugh liver function classification B, the presence of ascites, microvascular invasion, high ANXA2 expression, AFP, bilirubin and AST > upper limit of normal were associated with short OS in the univariate Cox proportional analysis." (PMID 34575275, 2021).
ataxia telangiectasia (1 paper, 2021). Ataxia-telangiectasia is the association of severe combined immunodeficiency (affecting mainly the humoral immune response) with progressive cerebellar ataxia. "A recent study suggested that nodular glomerulosclerosis partially results from DNA damage in the glomerulus, which induces collagen type VI secretion from human renal glomerular endothelial cells via ataxia telangiectasia and Rad3-related and ANXA2-mediated pathways." (PMID 34669736, 2021).
Behçet's disease (1 paper, 2015). "Moreover, vascular involvement was significantly higher in the anti-annexin A2 antibody-positive group versus the anti-annexin A2 antibody-negative group among all the clinical samples analyzed, indicating that annexin A2 is a novel endothelial cell membrane antigen involved in Behçet's disease." (PMID 25641213, 2015).
benign ovarian tumors (1 paper, 2021). "The diagnostic accuracy in distinguishing stage IA OC from benign ovarian tumors was almost twice as high for combined annexin A2 + CA125 (71.4%) in comparison to CA125 (37.1%) alone." (PMID 33406648, 2021). "In this study, we assessed the diagnostic performance of plasma annexin A2, either alone or in combination with CA125 in patients with OC, benign ovarian tumors and healthy controls." (PMID 33406648, 2021). "At 100% sensitivity, the specificity of diagnosing stage IA OC versus benign ovarian tumors was 63.6% compared to either annexin A2 (3.6% specificity) or CA125 (20% specificity) alone." (PMID 33406648, 2021). "Plasma annexin A2 levels were significantly higher in patients with stage I (1A-IC) cancers versus patients with benign ovarian tumors (2-fold increase, p = 0.0063)." (PMID 33406648, 2021). "The AUC for combined annexin A2 + CA125 in stage IA OC versus benign ovarian tumors was 0.920 and also larger than for either annexin A2 (AUC = 0.721) or CA125 (AUC = 0.838) alone." (PMID 33406648, 2021). "In stage I OC versus benign ovarian tumors, the AUC for combined annexin A2 + CA125 was 0.944 and larger than for either annexin A2 (AUC = 0.726) or CA125 (AUC = 0.903) alone." (PMID 33406648, 2021). "At 100% sensitivity, 45.5% specificity was achieved for combined annexin A2 + CA125 in stage I OC versus benign ovarian tumors, compared to either annexin A2 (3.6% specificity) or CA125 (20% specificity) alone." (PMID 33406648, 2021).
biliary atresia (1 paper, 2020). A rare, biliary tract disease characterized by progressive obliterative cholangiopathy of the intra- and extrahepatic bile ducts, occurring in the embryonic/ perinatal period, leading to severe and persistent neonatal jaundice and acholic stool. "Expression levels of ANXA2 as well as ANXA2P3 are also upregulated in liver tissues of biliary atresia patients, indicating that ANXA2P3 may be involved in the pathophysiology of biliary atresia development." (PMID 32154257, 2020).
bladder tumors (1 paper, 2021). "Whether ANXA2 plays the same role in bladder tumors needs further study." (PMID 34484309, 2021). "ANXA2, ANXA3, ANXA4, ANXA8, and ANXA9 were significantly increased in bladder tumor tissues, while ANXA6, ANXA7, and ANXA11 were significantly decreased." (PMID 34484309, 2021).
bleeding disorders (1 paper, 2023). "ANXA2 can modify various pathways involved in pathophysiological processes, including tumor cell invasion, metastasis, bleeding disorders, angiogenesis, and induction of inflammatory factor expression." (PMID 38141769, 2023). "Annexin A2 (ANXA2) is a member of the annexin family, which is expressed in almost all cells and exhibits various functions, including those related to cell invasion and metastasis, bleeding disorders, angiogenesis, and induction of inflammatory factors." (PMID 38141769, 2023).
brain injury (1 paper, 2022). Acute and chronic (see also brain INJURIES, CHRONIC) injuries to the brain, including the cerebral hemispheres, CEREBELLUM, and brain STEM. "ANXA2 has been shown to regulate the immune response by inhibiting activation and brain infiltration of peripheral leukocytes after traumatic brain injury." (PMID 36313990, 2022).
cardiac hypertrophy (1 paper, 2025). "While this study offers valuable insights into the mechanisms by which S100A10 and ANXA2 interact to regulate PE-induced myocardial hypertrophy, several limitations exist." (PMID 41195005, 2025). "Consistent with previous studies, we also detected the interaction between S100A10 and ANXA2 in NRVMs, and this interaction tended to be enhanced under the stimulation of PE, which may further confirm the role of ANXA2 in cardiac hypertrophy." (PMID 41195005, 2025).
carotid arterial thrombosis (1 paper, 2020). "An earlier study reported that the deletion of ANXA2 rendered mice susceptible to chemically-induced carotid arterial thrombosis." (PMID 32687500, 2020).
chronic hepatitis (1 paper, 2013). An active inflammatory process affecting the liver for more than six months. "They reported that ANXA2 is almost undetectable in normal liver and chronic hepatitis tissue, but the expression of ANXA2 is abundant in non-tumorous cirrhotic tissue at both the transcriptional and translational levels." (PMID 23950866, 2013).
chronic hepatitis B (1 paper, 2021). "Another report demonstrated that serum ANXA2 levels in chronic hepatitis B patients were significantly higher than those in the normal group." (PMID 34575275, 2021).
co-infection (1 paper, 2025). "ANXA2, found in endothelial cells, acts as an attachment receptor for co-infection." (PMID 40642060, 2025).
coccidiosis (1 paper, 2025). A parasitic infection caused by Coccidia. "This study establishes a foundation for further exploration of therapeutic targets to reduce host tissue damage, indicating that targeting ANXA2 may be a viable approach for controlling coccidiosis." (PMID 40777830, 2025). "The findings of this study establish a basis for additional research into the pathogenic mechanisms of E. tenella evasion and host pathogenesis, showing that targeting ANXA2 may be a viable approach for controlling coccidiosis." (PMID 40777830, 2025).
colorectal adenoma (1 paper, 2024). An adenoma that arises from the colon or rectum. "ANXA2 seems to also play an important role in colorectal adenomas with high-grade dysplasia, as well as in CCA." (PMID 39594718, 2024).